RPL26L1 (ribosomal protein L26 like 1)
Synonyms: RPL26P1
Tractability: PROTAC: UniProt records ubiquitination sites on it; ubiquitination databases record sites on it; its protein half-life has been measured.
Gene: Protein-coding gene on chromosome 5 (172,954,004 to 172,974,768, forward strand). Ensembl gene ENSG00000037241.
Subcellular location (Human Protein Atlas): Cytosol; Endoplasmic reticulum; Nucleoli
Pathways (Reactome):
Metabolism of proteins: Eukaryotic Translation Termination; Formation of a pool of free 40S subunits; GTP hydrolysis and joining of the 60S ribosomal subunit; L13a-mediated translational silencing of Ceruloplasmin expression; PELO:HBS1L and ABCE1 dissociate a ribosome on a non-stop mRNA; Peptide chain elongation; Ribosome Quality Control (RQC) complex extracts and degrades nascent peptide; SRP-dependent cotranslational protein targeting to membrane; ZNF598 and the Ribosome-associated Quality Trigger (RQT) complex dissociate a ribosome stalled on a no-go mRNA
Metabolism of RNA: Major pathway of rRNA processing in the nucleolus and cytosol; Nonsense Mediated Decay (NMD) enhanced by the Exon Junction Complex (EJC); Nonsense Mediated Decay (NMD) independent of the Exon Junction Complex (EJC)
Cellular responses to stimuli: Response of EIF2AK4 (GCN2) to amino acid deficiency
Developmental Biology: Regulation of expression of SLITs and ROBOs
Disease: Viral mRNA Translation
Metabolism: Selenocysteine synthesis
Gene Ontology:
Molecular function: protein binding; RNA binding; structural constituent of ribosome
Biological process: cytoplasmic translation; translation
Cellular component: extracellular exosome; cytosolic large ribosomal subunit; large ribosomal subunit; ribosome
Genetic constraint (gnomAD): Loss-of-function variants: 8 observed, 13.69 expected, observed/expected ratio (o/e) 0.58, 90% interval 0.34 to 1.05. The upper end of that interval is the gene's LOEUF score, 1.05, which puts it in group 4 of 6, group 1 being the genes least tolerant of losing a copy. Missense variants: 146 observed, 193.83 expected, observed/expected ratio (o/e) 0.75, 90% interval 0.66 to 0.86. Synonymous variants: 51 observed, 64.36 expected, observed/expected ratio (o/e) 0.79, 90% interval 0.63 to 1.
Homologues: Orthologues: chimpanzee RPL26L1 (100% identical), pig RPL26L1 (100% identical), rabbit RPL26L1 (100% identical), tropical clawed frog rpl26l1 (98% identical), zebrafish rpl26 (94% identical), guinea pig RPL26L1 (81% identical), Drosophila melanogaster RpL26 (72% identical), Caenorhabditis elegans rpl-26 (60% identical). Paralogues in human: RPL26 (99% identical).
Diseases named in the same sentence as RPL26L1 in open-access papers:
RPL26L1 is named in the same sentence as 10 diseases in open-access papers, as found by Europe PMC text mining. Sharing a sentence is not in itself a finding about the gene and the disease. The quoted sentences say what the papers report.
breast carcinoma (1 paper, 2016). "A classifier combining the expression signature of RPL39L, RPL26L1, and RPL21 has an even greater predictive power, comparable to that of genes that are most predictive for the relapse-free survival of breast cancer patients." (PMID 27884178, 2016).
thyroid carcinomas (1 paper, 2016). "Among these, RPL26L1 and RPS27L were exclusively up-regulated in breast and thyroid carcinomas, respectively, whereas RPL21 had decreased expression in breast and uterine cancers." (PMID 27884178, 2016).
RPL26L1 also shares sentences with these, for which no sentence is quoted: Alzheimer disease (1 paper); cancer (1); endometrial cancer (1); mantle cell lymphoma (1); polycystic ovary syndrome (1); systemic lupus erythematosus (1); uterine cancer (1); vitiligo (1).